TSR1 (TSR1 ribosome maturation factor)
Description:
Required during maturation of the 40S ribosomal subunit in the nucleolus.
Synonyms: FLJ10534
Tractability: Small molecule: a structure with a bound ligand is known. PROTAC: ubiquitination databases record sites on it; its protein half-life has been measured.
Gene: Protein-coding gene on chromosome 17 (2,322,392 to 2,336,657, reverse strand). Ensembl gene ENSG00000167721.
Subcellular location: Nucleus, nucleolus
Subcellular location (Human Protein Atlas): Nucleoplasm
Pathways (Reactome):
Metabolism of RNA: Major pathway of rRNA processing in the nucleolus and cytosol
Gene Ontology:
Molecular function: protein binding; RNA binding; GTPase activity
Biological process: endonucleolytic cleavage of tricistronic rRNA transcript (SSU-rRNA, 5.8S rRNA, LSU-rRNA); maturation of SSU-rRNA from tricistronic rRNA transcript (SSU-rRNA, 5.8S rRNA, LSU-rRNA); ribosome biogenesis
Cellular component: 90S preribosome; cytosol; nucleolus; nucleoplasm; nucleus
Genetic constraint (gnomAD): Loss-of-function variants: 81 observed, 93.13 expected, observed/expected ratio (o/e) 0.87, 90% interval 0.73 to 1.05. The upper end of that interval is the gene's LOEUF score, 1.05, which puts it in group 4 of 6, group 1 being the genes least tolerant of losing a copy. Missense variants: 988 observed, 1,027.3 expected, observed/expected ratio (o/e) 0.96, 90% interval 0.91 to 1.01. Synonymous variants: 362 observed, 362.34 expected, observed/expected ratio (o/e) 1, 90% interval 0.92 to 1.09.
Homologues: Orthologues: chimpanzee TSR1 (99% identical), macaque TSR1 (98% identical), pig TSR1 (90% identical), rabbit TSR1 (89% identical), dog TSR1 (88% identical), mouse Tsr1 (86% identical), rat Tsr1 (84% identical), guinea pig TSR1 (81% identical), tropical clawed frog tsr1 (67% identical), Drosophila melanogaster Tsr1 (44% identical), Caenorhabditis elegans tag-151 (39% identical), zebrafish tsr1 (19% identical). Paralogues in human: BMS1 (22% identical).
Diseases named in the same sentence as TSR1 in open-access papers:
TSR1 is named in the same sentence as 10 diseases in open-access papers, as found by Europe PMC text mining. Sharing a sentence is not in itself a finding about the gene and the disease. The quoted sentences say what the papers report.
melanoma (2 papers, 2018 to 2020). A malignant, usually aggressive tumor composed of atypical, neoplastic melanocytes. "Finally, ADAMTS5's recombinant TSR1 inhibits the growth of melanoma in mice by anti-angiogenesis mechanism, and ADAMTS5 can also be used as a prognostic biomarker for prostate cancer." (PMID 33123466, 2020).
lymphoma (1 paper, 2022). A malignant (clonal) proliferation of B- lymphocytes or T- lymphocytes which involves the lymph nodes, bone marrow and/or extranodal sites. "The HPA database results showed that the protein levels of TSR1, WDR46, HSP90AA1, and NOP56 in lymphoma were higher than those in normal lymphoid tissue, whereas the protein level of UBC in lymphoma was lower than that in normal lymphoid tissue." (PMID 35263200, 2022).
pancreatic cancer (1 paper, 2024). "Seven genes were identified in mass spectrometry and bioinformatic analysis, all significantly downregulated in pancreatic cancer (GEO data, GSE32676), including TSPYL2, TSR1, METAP2, CYR61, EBF2, CIRBP, and TGFBR3." (PMID 38015024, 2024).
sarcoma (1 paper, 2020). A usually aggressive malignant neoplasm of the soft tissue or bone. "In summary, here we demonstrate that ISG15, NUP50, PTTG1, SERPINE1, and TSR1 are highly expressed in sarcoma tissues and associated with sarcoma metastasis and poor prognosis." (PMID 33123466, 2020). "The results of immunohistochemistry indicated that SG15, NUP50, PTTG1, SERPINE1, and TSR1 were highly expressed in sarcoma tissues." (PMID 33123466, 2020). "The results of qRT-PCR suggested that ISG15, NUP50, PTTG1, SERPINE1, and TSR1 were highly expressed in sarcoma tissues." (PMID 33123466, 2020). "To validate whether ISG15, NUP50, PTTG1, SERPINE1, and TSR1 are differentially expressed in sarcoma tissues, we experimentally validated their expression in the tissues of 10 sarcoma patients." (PMID 33123466, 2020). "Taken together, results of these experiments suggest that high expression levels of ISG15, NUP50, PTTG1, SERPINE1, and TSR1 exert a positive regulatory effect on metastasis, suggesting poor prognosis, and that Tanespimycin may effectively treat LMS sarcoma subtype." (PMID 33123466, 2020).
cancer (6 papers, 2022 to 2025). A tumor composed of atypical neoplastic, often pleomorphic cells that invade other tissues. "However, the tumorigenesis through metabolism of SLC family and the anti-angiogenesis of TSR1 confirmed in other cancers showed potential interactions between each of them and ALDH2." (PMID 36144737, 2022). "Thus, the cancer-associated Rps15_S136F mutation, which leads to increased misinitiation at non-AUG codons, may perturb Rps15 directly, or affect how Ltv1 (or other, yet undescribed factors) regulates the interaction between Rps15 and the loop in Tsr1." (PMID 37503067, 2023). "Notably, the pre-rRNA-processing protein TSR1 homolog (TSR1), when used in conjunction with PSA, proved to be superior to PSA alone in terms of cancer categorization." (PMID 38201450, 2023).
tumor (2 papers, 2022 to 2025). "The expression levels of mRNA and proteins of TSR1, WDR46, HSP90AA1, and NOP56 in DLBCL were significantly higher than those in normal tissues, suggesting that these four hub genes can be activated and can upregulate the expression of mRNA during tumor development." (PMID 35263200, 2022).
TSR1 also shares sentences with these, for which no sentence is quoted: Coronary artery dissection (1 paper); inflammatory bowel disease (1); meningioma (1); prostate carcinoma (1).